DPEP3 (dipeptidase 3)
Description:
Lacks dipeptidase activity and is unable to hydrolyze cystinyl-bis-glycine, leukotriene D4 and the beta-lactam antibiotic imipenem. The absence of activity may be due to the inability of asparagine (instead of aspartate found in DPEP1/2) at position 359 to function as the acid/base catalyst and activate the nucleophilic water/hydroxide. A tyrosine (instead of histidine) at position 269 reduces affinity for the beta zinc and may cause substrate steric hindrance.
Synonyms: MBD3
Tractability: Small molecule: it belongs to a druggable protein family. Antibody: UniProt predicts a signal peptide or a membrane-spanning region; its Gene Ontology location is reachable by antibodies, with medium confidence.
Gene: Protein-coding gene on chromosome 16 (67,975,663 to 67,980,554, reverse strand). Ensembl gene ENSG00000141096.
Subcellular location: Membrane
Gene Ontology:
Molecular function: dipeptidase activity; peptidase activity
Biological process: leukotriene D4 catabolic process; proteolysis
Cellular component: acrosomal vesicle; membrane; plasma membrane
Genetic constraint (gnomAD): Loss-of-function variants: 42 observed, 49.53 expected, observed/expected ratio (o/e) 0.85, 90% interval 0.66 to 1.1. The upper end of that interval is the gene's LOEUF score, 1.1, which puts it in group 4 of 6, group 1 being the genes least tolerant of losing a copy. Missense variants: 560 observed, 664.19 expected, observed/expected ratio (o/e) 0.84, 90% interval 0.79 to 0.9. Synonymous variants: 276 observed, 283.86 expected, observed/expected ratio (o/e) 0.97, 90% interval 0.88 to 1.07.
Homologues: Orthologues: chimpanzee DPEP3 (99% identical), macaque DPEP3 (94% identical), pig DPEP3 (73% identical), rat Dpep3 (72% identical), mouse Dpep3 (72% identical), dog DPEP3 (72% identical), guinea pig DPEP3 (67% identical), Drosophila melanogaster CG44837 (38% identical), Drosophila melanogaster CG6154 (35% identical). Paralogues in human: DPEP2 (70% identical), DPEP1 (37% identical).
Diseases named in the same sentence as DPEP3 in open-access papers:
DPEP3 is named in the same sentence as 11 diseases in open-access papers, as found by Europe PMC text mining. Sharing a sentence is not in itself a finding about the gene and the disease. The quoted sentences say what the papers report.
ovarian carcinoma (2 papers, 2025). A malignant neoplasm originating from the surface ovarian epithelium. "Anti-DPEP3 ADCs represent an innovative therapeutic approach targeting DPEP3, a membrane-bound glycoprotein associated with TICs in ovarian cancer." (PMID 41347223, 2025). "In these studies, a single dose of SC-003 was sufficient to induce tumor regression, highlighting its potential as a therapeutic option for patients with advanced DPEP3-positive ovarian cancer." (PMID 41347223, 2025).
COVID-19 (1 paper, 2022). A disease caused by infection with severe acute respiratory syndrome coronavirus 2. "Dipeptidase 3 (DPEP3) that encodes a membrane-bound protein in testicular germ cells, which may be important for testicular function and is downregulated in convalescent male COVID-19 patients, likely contributing to compromised fertility in them." (PMID 36143338, 2022).
endometriosis (1 paper, 2025). The growth of functional endometrial tissue in anatomic sites outside the uterine body. "Another enriched pathway across the four conditions is ‘arachidonic acid metabolism’; of the five endometriosis genes enriched in this pathway, four are shared with the other three immune conditions, namely, DPEP3, GPX1, DPEP2, and PON2." (PMID 40262193, 2025).
varicocele (1 paper, 2022). A condition characterized by the dilated tortuous veins of the spermatic cord with a marked left-sided predominance. "Next, we used western blotting to compare the levels of DPEP3, a key enzyme involved in testicular dipeptide metabolism, in the normal group, varicocele group, and varicocelectomy group." (PMID 35338186, 2022). "Western blotting confirmed the downregulation of DPEP3 (dipeptidase 3) in the varicocele group and the upregulation of DPEP3 in the varicocelectomy group." (PMID 35338186, 2022). "Further study found that DPEP3, the key enzyme of dipeptides degradation, had significant changes in normal group, varicocele group and varicocelectomy group." (PMID 35338186, 2022). "We also found that DPEP3 was expressed in sperm and that levels of this dipeptidase were reduced in varicocele patients." (PMID 35338186, 2022). "How DPEP3 regulates the dipeptide level and amino acid profile in semen of patients with varicocele remains to be further studied." (PMID 35338186, 2022). "DPEP3 was downregulated in the varicocele group but upregulated in the varicocelectomy group." (PMID 35338186, 2022).
tumor (4 papers, 2022 to 2025). "The isolation of the tumour initiating cells subpopulation from patient-derived xenograft EOC models led to the identification of DPEP3 as a tumour initiating cell associated protein." (PMID 35774118, 2022). "Key findings include the identification of various ADCs targeting specific tumor-associated antigens — such as FRα, HER2, TROP2, and DPEP3 — which have shown promising efficacy in clinical trials." (PMID 41347223, 2025). "The observed upregulation of DPEP3 and THRSP in high-grade tumors aligns with their established roles in tumor progression and metabolic reprogramming, while the downregulation of differentiation markers like KRT33A suggests a loss of epithelial characteristics in aggressive disease." (PMID 41155123, 2025). "Notably, DPEP3 (dipeptidase 3), THRSP (thyroid hormone responsive), and SLC5A8 (solute carrier family 5 member 8) were significantly upregulated in high-grade tumors, suggesting roles in tumor progression and metabolic reprogramming." (PMID 41155123, 2025).
cancer (2 papers, 2021 to 2023). A tumor composed of atypical neoplastic, often pleomorphic cells that invade other tissues. "Of 90 CTAs validated by RNA sequencing, eight CTAs (DPEP3, EZHIP, MAGEA4, MAGEB2, MAGEC2, PAGE1, PRAME, and TKTL1) were selected for immunohistochemical profiling in cancer tissues from 328 NSCLC patients." (PMID 37341056, 2023).
DPEP3 also shares sentences with these, for which no sentence is quoted: Azoospermia (1 paper); B-cell lymphoma (1); colorectal tumor (1); melanoma (1); ovarian serous cystadenocarcinoma (1).